CCNE1 (cyclin E1)
Diseases named in the same sentence as CCNE1 in open-access papers (continued):
Sharing a sentence is not in itself a finding about the gene and the disease.
metastatic tumors (6 papers, 2019 to 2025). "We further examined the association of CCNE1 gene expression and CCNE1 gene amplification in both primary and metastatic tumors." (PMID 30665374, 2019). "The mean frequency of CCNE1 gene amplification in metastatic tumors was 8.12%, whereas that in primary tumors was 5.86% (P < 0.05)." (PMID 41331376, 2025). "Each complete patient case included two to five metastatic disease sites for evaluation of CCNE1 copy number yielding 18 total metastatic sites for testing." (PMID 34485660, 2021). "Further analysis of an independent cohort of “Discovery-TNBC” revealed CCNE1 amplification (CN ≥ 6) in 6 of 55 (10.9%) patients (primary and metastatic tumors)." (PMID 30665374, 2019). "Cox proportional hazard regression analysis of PFS according to the signatures of CDK6, p-CDK2 and cyclin E1 and clinicopathological parameters of the metastatic disease showed that the combined biomarkers signature was an independent prognostic factor of PFS in both tested cohorts." (PMID 36153348, 2022). "Our data that CCNE1 amplification remains present in the metastatic disease sites provides support that molecularly targeted approaches could be therapeutically active in advanced disease." (PMID 34485660, 2021). "However, the mean CCNE1 expression in metastatic tumors was increased compared to primary tumors (expression = 5.29 vs. 3.87, SD = 0.49 vs. 2.02)." (PMID 30665374, 2019). "In GB-S9, amplification of cell cycle-related oncogenes CDKN1B and CCNE1 was uniformly observed from primary GBAC to regional and distant metastatic tumors." (PMID 36476508, 2022). "In tumors with no CCNE1 amplification (CN < 6), the mean and variance of CCNE1 mRNA expression were comparable between primary and metastatic tumors." (PMID 30665374, 2019).
neuroblastoma (5 papers, 2017 to 2024). Neuroblastoma (NB) is the most common solid, extracranial childhood tumor. "Paediatric neuroblastoma patients with an age at diagnosis < 18 months and with CCNE1 higher expression levels had the most diverse prognosis than other subgroups." (PMID 35655142, 2022). "The Kaplan–Meier survival analysis further showed that overall survival was decreased in paediatric neuroblastoma patients with high CCNE1, CDK2 or CHEK2 expression." (PMID 35655142, 2022). "Combinations of CCNE1 with age at diagnosis or combinations of SESN1 with age at diagnosis achieved superior prognostic effects in paediatric neuroblastoma." (PMID 35655142, 2022). "CCNE1 was an independent prognostic factor, and combinations of CCNE1 expression with age at diagnosis achieved better prognostic effects in neuroblastoma." (PMID 35655142, 2022). "Paediatric neuroblastoma patients with an age at diagnosis < 18 months and with CCNE1 lower expression levels had significantly better prognosis and mostly survived in the following timeframe." (PMID 35655142, 2022). "In contrast, paediatric neuroblastoma patients with an age at diagnosis ≥ 18 months and with higher CCNE1 expression levels had a significantly worse prognosis." (PMID 35655142, 2022). "Paediatric neuroblastoma patients with an age at diagnosis ≥ 18 months and with CCNE1 lower expression levels had medium overall survival risks." (PMID 35655142, 2022). "First, in the TARGET, E-MTAB-161, E-MTAB-1781, E-MTAB-8248, E-TABM-38, GSE49710 and GSE85047 datasets, the expression levels of CCNE1 were higher in paediatric neuroblastoma patients with an age at diagnosis ≥ 18 months than in paediatric neuroblastoma patients with an age at diagnosis < 18 months." (PMID 35655142, 2022). "Our results were consistent with these observations that CCNE1 was upregulated in MYCN-amplified paediatric neuroblastoma patients, and CCNE1 overexpression was associated with worse clinical outcomes of paediatric neuroblastoma." (PMID 35655142, 2022).
neuroblastoma (continued). "Furthermore, based on the expression levels of CCNE1 and age at diagnosis, paediatric neuroblastoma patients in each dataset were divided into four subgroups." (PMID 35655142, 2022). "Moreover, CCNE1 was a prognostic factor of paediatric neuroblastoma in the E-MTAB-161, E-MTAB-1781, E-MTAB-8248, GSE16476 and GSE49710 datasets, independent of MYCN amplification and age at diagnosis." (PMID 35655142, 2022). "Furthermore, our results showed that CCNE1 was also overexpressed in paediatric neuroblastoma patients with an age at diagnosis ≥ 18 months." (PMID 35655142, 2022). "Combinations of CCNE1 expression and SESN1 expression with age at diagnosis achieved a better prognosis of neuroblastoma." (PMID 35655142, 2022). "The results were consistent with overexpression of CCNE1, CDK2 or CHEK2 being worse prognostic factors, while increased regulation of SESN1 was a better prognostic factor in paediatric neuroblastoma." (PMID 35655142, 2022). "CCNE1 was also highly expressed in paediatric neuroblastoma patients with an age at diagnosis ≥ 18 months, while SESN1 was downregulated in paediatric neuroblastoma patients with an age at diagnosis ≥ 18 months." (PMID 35655142, 2022). "CCNE1, SESN1, MYCN amplification and age at diagnosis were independent prognostic markers of neuroblastoma." (PMID 35655142, 2022). "In contrast to CCNE1, CDK2 and CHEK2, SESN1 had opposite expression levels and prognostic effects in paediatric neuroblastoma." (PMID 35655142, 2022). "Overall, age at diagnosis, MYCN amplification, CCNE1 and SESN1 were independent prognostic factors in at least four independent paediatric neuroblastoma cohorts." (PMID 35655142, 2022). "Higher expression of CCNE1, CDK2 or CHEK2 was an unfavourable prognostic factor, while higher expression of SESN1 was a favourable prognostic factor in paediatric neuroblastoma." (PMID 35655142, 2022). "Previous results have shown that CCNE1 is a target of MYCN and an unfavourable prognostic marker of neuroblastoma." (PMID 35655142, 2022). "We specifically studied MYCN, MYBL2, BIRC5, BARD1 and AURKA, poor prognosis markers of neuroblastoma, and CCNA2 and CCNE1 genes, involved in general carcinogenesis." (PMID 28467792, 2017).
neuroblastoma (continued). "However, the prognostic effects of CCNE1, CDK2, CHEK2 and SESN1 were different in paediatric neuroblastoma." (PMID 35655142, 2022). "Combinations of CCNE1 and SESN1 with age at diagnosis achieved superior prognosis of neuroblastoma." (PMID 35655142, 2022). "Since CCNE1 was a prognostic maker of neuroblastoma independent of age at diagnosis, the combinations of CCNE1 with age at diagnosis could achieve better prognostic effects in patients with paediatric neuroblastoma." (PMID 35655142, 2022). "The mRNA expression levels of CCNE1, CDK2, CHEK2 and SESN1 in paediatric neuroblastoma patients with or without MYCN amplification were also investigated." (PMID 35655142, 2022).
psoriasis (5 papers, 2020 to 2025). An autoimmune condition characterized by red, well-delineated plaques with silvery scales that are usually on the extensor surfaces and scalp. "Taking the intersection of these two algorithms, we finally obtained four specific gene biomarkers for psoriasis diagnosis (UGGT1\MMP9\CCNE1\ARHGEF28)." (PMID 38803495, 2024). "Specifically, LINC02159 showed a positive correlation with CCNB1, whereas LINC01206 was positively correlated with both CCNB1 and CCNE1, suggesting that upregulated lncRNAs may coordinate with cell cycle genes to drive psoriasis progression." (PMID 40670887, 2025). "Further we analyzed the expression of the four diagnostic genes screened by the two machine algorithms in 10 major immune cells and found that CCNE1 was elevated in CD4+ T cells as well as neutrophils in psoriasis lesions, and ARHGEF28 was elevated in mast cells." (PMID 38803495, 2024). "Finally, we confirmed that miR-26a-5p triggered cascade downregulation of biomarkers from the IL-23/IL-17A axis associated with psoriasis development while suppressing CDC6 and CCNE1 expression." (PMID 38446584, 2024). "Mechanistic investigations revealed that miR-26a-5p induced a cascade of downregulated genes associated with the IL-23/IL-17A axis, which is known to be critical in psoriasis pathogenesis, while concomitantly suppressing CDC6 and CCNE1 expression." (PMID 38446584, 2024). "RT-qPCR results showed that compared to normal human epidermis, the expression of UGGT1, CCNE1, and MMP9 was significantly increased in patients with psoriasis, while ARHGEF28 expression was significantly decreased." (PMID 38803495, 2024). "It has been demonstrated that IL-17A stimulates keratinocytes to upregulate the cell cycle-related genes, such as CCNE1, which made contribution to epidermal KC proliferation, therefore we hypothesize that enhanced IL-17 may contribute to the elevated CCNE1 in epidermal cells of psoriasis patients." (PMID 38803495, 2024).
thyroid cancer (5 papers, 2020 to 2023). "NVP-BEZ235 treatment significantly decreased the protein expression of cyclin E1 and Cdk2 in the human thyroid cancer cell lines in a time-dependent manner." (PMID 32025215, 2020). "To summarize, the upregulation of Cyclins D with stabilization of activated (T172-phosphorylated) CDK4 complexes and the upregulation of Cyclin E1 with increase of its kinase activity are most probably the mechanisms that bypass CDK4/6 inhibition in thyroid cancer cells." (PMID 37964967, 2023). "Besides, the bioinformatic analysis found that genes related to the cell cycle (i.e., CDKN2A, CDKN2B, CCNE1, etc.)were mutated or abnormally expressed in ATC, which might provide another thought in advanced thyroid cancers." (PMID 34900720, 2021). "Furthermore, canagliflozin inhibited G1/S phase transition and cyclin D1, cyclin D3, cyclin E1, cyclin E2, and E2F1 expression levels in thyroid cancer cell." (PMID 35148777, 2022).
endometrial tumors (4 papers, 2020 to 2025). "Given CCNE1 amplification’s prevalence in over half of analyzed high-grade endometrial tumors, it’s conceivable to consider these molecules in strategies for managing such tumors." (PMID 38564163, 2024). "The discovery of CCNE1 amplification in most high-grade endometrial tumors provides a promising avenue for therapy." (PMID 38564163, 2024). "In addition, pathway analysis and clustering of the endometrial tumors in the TCGA data set revealed that dysregulation of mitotic processes is a frequent occurrence in USC, including increase in cyclin B1, CDK1 and cyclin E1 protein expression." (PMID 31906456, 2020).
esophageal cancer (4 papers, 2013 to 2025). A primary or metastatic malignant neoplasm involving the esophagus. "It was suggested that Smad3-P27/P21-cyclin E1/CDK2-phosphorylated retinoblastoma protein pathways might be involved in IGFBP-3-mediated radiosensitivity transition in esophageal squamous cell carcinoma (ESCC) the most prevalent histologic type of esophageal cancer in China and eastern countries." (PMID 27978831, 2016).
gynecological cancers (4 papers, 2021 to 2025). "CCNE1 amplification is enriched in aggressive histologic subtypes of gynecological cancers and is linked to epithelial-specific expression and immune exclusion." (PMID 41331376, 2025). "Here, the authors identify that CCNE1-amplified gynecological cancer is sensitive to combined PKMYT1 and ATR inhibition via CDK1 activation, resulting in premature mitosis, DNA damage, cell apoptosis and reduced tumour growth and metastasis." (PMID 40169546, 2025). "CCNE1 is commonly amplified in gynecological cancers such as OVCA and EMCA, and effective treatments exploiting this genomic alteration are lacking." (PMID 40169546, 2025). "CCNE1 is commonly amplified in gynecological cancers such as OVCA and EMCA, and effective treatments exploiting this genomic alteration are currently lacking." (PMID 38410486, 2024). "Given this unmet clinical need, we sought to identify a treatment strategy that targets critical survival pathways for CCNE1-amplified dependent gynecological cancers." (PMID 38410486, 2024). "CCNE1 amplification reflects molecular features of aggressive gynecological cancer subtypes and may inform patient stratification in targeted therapy studies, though its predictive utility requires further clinical validation." (PMID 41331376, 2025).
multiple myeloma (4 papers, 2016 to 2023). "Of interest, the sensitivity of myeloma cells to seliciclib was reported to be associated with cyclin E1 expression; with high cyclin E1 expression correlating with a low sensitivity." (PMID 29163849, 2017). "Furthermore, results of a study that applied proteasome inhibitor bortezomib as first-line therapy against multiple myeloma indicate that it could also be considered as a potential therapeutic approach for TNBC with CCNE1 amplification." (PMID 33194720, 2020).
oral squamous cell carcinoma (4 papers, 2010 to 2025). "In a previous study, we found that LINC00839 acts as an oncogene in oral squamous cell carcinoma (OSCC) through the miR-195-5p/cyclin E1 axis." (PMID 41141624, 2025). "We also retained several potential multitarget miRNAs for later studies, such as miR-195-5p, which, like miR-26a-5p, also interferes with CDC6 and CCNE1, as demonstrated in oral squamous cell carcinoma cell lines." (PMID 38446584, 2024).
pancreatic ductal adenocarcinoma (4 papers, 2014 to 2022). An infiltrating adenocarcinoma that arises from the epithelial cells of the pancreas. "The possible reduction of YBX1 cytoplasmic availability inhibits proliferation of myeloid differentiation-inducing apoptosis and decreases the expression of cyclin D1 and cyclin E1 associated with pancreatic ductal adenocarcinoma cell growth." (PMID 36066672, 2022). "Through the GSK3B/Cyclin D1/Cyclin E1 pathway, YBX1 depletion induces apoptosis and decreases cyclin D1 and cyclin E1 protein expression, resulting in a reduction in Pancreatic Ductal Adenocarcinoma growth." (PMID 36066672, 2022).
uterine cancer (4 papers, 2022 to 2024). Primary or metastatic malignant neoplasm involving the uterine corpus and/or the cervix. "CCNE1 has the highest genetic change frequency in uterine carcinoma patients (40%)." (PMID 39591374, 2024).
carcinosarcoma (3 papers, 2018 to 2025). A malignant tumor composed of a mixture of carcinomatous and sarcomatous elements. "Similarly, in a large institutional cohort of 2,042 ECs analyzed by targeted massive parallel sequencing, CCNE1 amplification was detected in 22% of cases, most of which were serous and carcinosarcoma." (PMID 41331376, 2025).
cholangiocarcinoma (3 papers, 2021 to 2023). A carcinoma that arises from the intrahepatic biliary tree (intrahepatic cholangiocarcinoma) or from the junction, or adjacent to the junction, of the right and left hepatic ducts (hilar cholangiocarcinoma). "In a different murine model in which the NOTCH1 ICD is expressed in the neonatal liver, cholangiocarcinoma initiation and growth promote the transcriptional regulation of Cyclin-E (CCNE1)." (PMID 37605966, 2023).
Cirrhosis (3 papers, 2016 to 2021). A chronic disorder of the liver in which liver tissue becomes scarred and is partially replaced by regenerative nodules and fibrotic tissue resulting in loss of liver function. "Finally, we believe that viral insertions and structural rearrangements activating CCNA2 or CCNE1 are early events triggering hepatocarcinogenesis because they occur in patients without cirrhosis and in absence of other oncogenic event like CTNNB1 mutations." (PMID 30531861, 2018).